MAP4K4 (mitogen-activated protein kinase kinase kinase kinase 4)
Description:
Serine/threonine kinase that plays a role in the response to environmental stress and cytokines such as TNF. Appears to act upstream of the JUN N-terminal pathway. Activator of the Hippo signaling pathway which plays a pivotal role in organ size control and tumor suppression by restricting proliferation and promoting apoptosis. MAP4Ks act in parallel to and are partially redundant with STK3/MST2 and STK4/MST2 in the phosphorylation and activation of LATS1/2, and establish MAP4Ks as components of the expanded Hippo pathway. Phosphorylates SMAD1 on Thr-322.
Synonyms: HGK; NIK; FLH21957; HEL-S-31; MEKKK4
Tractability: Small molecule: a structure with a bound ligand is known; a high-quality ligand is known; it belongs to a druggable protein family. PROTAC: ubiquitination databases record sites on it; its protein half-life has been measured; a small molecule that binds it is known.
Target class: Kinase; STE protein kinase group; STE protein kinase STE20 family; STE protein kinase MSN subfamily; Protein Kinase; Enzyme
Safety:
Unwanted effects reported when the protein is acted on. In parentheses: how it was acted on, where the effect was seen, and who reports it.
bone fractures (source: ClinPGx)
Gene: Protein-coding gene on chromosome 2 (101,696,850 to 101,894,690, forward strand). Ensembl gene ENSG00000071054.
Subcellular location: Cytoplasm
Pathways (Reactome):
Cellular responses to stimuli: Oxidative Stress Induced Senescence
Gene Ontology:
Molecular function: ATP binding; creatine kinase activity; MAP kinase kinase kinase kinase activity; microtubule binding; protein binding; protein serine kinase activity; protein serine/threonine kinase activity; protein kinase activity
Biological process: intracellular signal transduction; negative regulation of apoptotic process; positive regulation of cell migration; positive regulation of hippo signaling; protein phosphorylation; regulation of JNK cascade; MAPK cascade; negative regulation of cell-matrix adhesion; neuron projection morphogenesis; positive regulation of ARF protein signal transduction; positive regulation of focal adhesion assembly; positive regulation of focal adhesion disassembly; positive regulation of keratinocyte migration; regulation of MAPK cascade; positive regulation of intracellular signal transduction
Cellular component: cytoplasm; focal adhesion
Genetic constraint (gnomAD): Loss-of-function variants: 32 observed, 139.73 expected, observed/expected ratio (o/e) 0.23, 90% interval 0.17 to 0.31. The upper end of that interval is the gene's LOEUF score, 0.31, which puts it in group 1 of 6, group 1 being the genes least tolerant of losing a copy. Missense variants: 928 observed, 1,460.3 expected, observed/expected ratio (o/e) 0.64, 90% interval 0.6 to 0.67. Synonymous variants: 544 observed, 537.37 expected, observed/expected ratio (o/e) 1.01, 90% interval 0.94 to 1.09.
Homologues: Orthologues: rat Map4k4 (98% identical), dog MAP4K4 (97% identical), chimpanzee MAP4K4 (96% identical), macaque MAP4K4 (95% identical), rabbit MAP4K4 (94% identical), pig MAP4K4 (94% identical), tropical clawed frog map4k4 (93% identical), mouse Map4k4 (88% identical), guinea pig MAP4K4 (81% identical), zebrafish map4k4 (65% identical). Paralogues in human: TNIK (67% identical), MINK1 (63% identical), NRK (35% identical), SLK (20% identical), MAP4K3 (19% identical), STK10 (17% identical), TAOK1 (17% identical), MAP4K5 (17% identical), MAP4K2 (16% identical), MAP4K1 (16% identical), TAOK2 (15% identical), TAOK3 (15% identical), and 23 more.
Diseases named in the same sentence as MAP4K4 in open-access papers:
MAP4K4 is named in the same sentence as 109 diseases in open-access papers, as found by Europe PMC text mining. Sharing a sentence is not in itself a finding about the gene and the disease. The quoted sentences say what the papers report.
pancreatic cancer (21 papers, 2016 to 2025). "Recent understanding of MAP4K4 in malignant diseases suggests a critical role of MAP4K4 in glioblastoma, colon, prostate and pancreatic cancers and associated cachexia." (PMID 37190200, 2023). "MAP4K4 is associated with pancreatic cancer development and correlates with poor clinical outcomes." (PMID 36683274, 2023). "MAP4K4 is also overexpressed in patients with pancreatic cancer and could represent a biomarker associated with poor clinical prognosis." (PMID 37223681, 2023). "The present review will discuss the functional role of the most-studied MAP4K member, MAP4K4, in inflammatory and malignant diseases, including glioblastoma, colon, prostate, and pancreatic cancers and cancer-associated cachexia, and its possible use in targeted therapy." (PMID 37190200, 2023). "For example, MAP4K4 has been shown to function as an oncogene in several cancer types, including colorectal and pancreatic cancers, where it promotes cell proliferation, migration and metastasis." (PMID 41034525, 2025). "In a murine model of pancreatic cancer, the pharmacological inhibition of MAP4K4 with GNE-495 suppressed pancreatic cell growth and tumor migration." (PMID 39941781, 2025). "The MAP4K4-specific inhibitor GNE-495 exerts multiple therapeutic effects against pancreatic cancer, including inhibiting cell proliferation, inducing apoptosis, and reducing tumour stroma." (PMID 41463025, 2025). "MAP4K4 regulates pancreatic cancer cell proliferation via its downstream target, MLK3, and perhaps other targets." (PMID 37190200, 2023). "Cell viability and cell growth assays were performed to assess the anti-cancer effect of the identified MAP4K4 inhibitor, F389-0746, in human pancreatic cancer cells." (PMID 36683274, 2023). "Overexpression of MAP4K4 is frequently reported in many cancers, including glioblastoma, colon, prostate, and pancreatic cancers." (PMID 37190200, 2023). "In a murine model of pancreatic cancer, specific pharmacological inhibition of MAP4K4 with GNE-495 inhibited pancreatic cell growth and tumor migration." (PMID 37223681, 2023). "MAP4K4 is overexpressed in multiple tumor types such as pancreatic cancer, colorectal cancer, ovarian epithelial cancer, lung cancer, gastric cancer, and hepatocellular carcinoma." (PMID 37223681, 2023). "MAP4K4 was demonstrated to promote pancreatic cancer cell growth and proliferation by activating downstream MKK4-JNK-AP-1 signalling, which enhances the translation of proliferative proteins and cytokines." (PMID 36683274, 2023). "The high expression of MAP4K4 in pancreatic cancer was strongly correlated with poor OS and recurrence-free survival in clinical cases." (PMID 36683274, 2023). "The downregulated MAP4K4 expression promotes the antitumor effect and decreases drug resistance in pancreatic cancer." (PMID 37190200, 2023). "Along with the inhibition of MAP4K4 activity, cell apoptosis markers were induced, leading to pancreatic cancer cell death." (PMID 36683274, 2023). "Clinicopathologic evidence also suggests that MAP4K4 overexpression in pancreatic cancer strongly correlates with poor overall survival and recurrence-free survival." (PMID 36683274, 2023). "The overexpression of MAP4K4 is reported in various cancers, including lung, liver, prostate, ovarian, and pancreatic cancers." (PMID 37190200, 2023). "In parallel, in vitro results demonstrated that inhibition of MAP4K4 (through the use of RNA interference with miR-98-5p) reduced the proliferation of pancreatic cancer cells." (PMID 37223681, 2023). "In pancreatic cancer, nearly half of patients were found to overexpress MAP4K4 in the pancreas compared to healthy individuals." (PMID 36683274, 2023). "Loss of function studies in gastric, hepatocellular carcinoma, prostate cancer and pancreatic cancer cells indicated tumorigenic and growth-promoting activities of MAP4K4." (PMID 36568222, 2022).
pancreatic cancer (continued). "Another study demonstrated that miR-141-3p can directly target MAP4K4 to repress pancreatic carcinoma cell invasion." (PMID 35039872, 2022). "To re-confirm our IHC/IF results with pancreatic tissues from KPC mice, the saline or GNE-495-treated pancreatic tumor extracts were blotted with antibodies for MAP4K4, MLK3, PCNA, α-SMA, cleaved caspase 3, c-PARP, Bax, and Bcl2." (PMID 34511598, 2021). "The MLK3 phosphorylation by MAP4K4 consequently promotes pancreatic cancer cell proliferation, colony formation, and cell migration." (PMID 34511598, 2021). "Once the stable cell lines were characterized, we used them to determine the impact of MLK3 phosphorylation by MAP4K4 on pancreatic cancer cell proliferation, colony formation, and cell migration." (PMID 34511598, 2021). "Our data suggest that MLK3 is a direct downstream substrate of MAP4K4 that supports pancreatic cancer development via phosphorylating MLK3." (PMID 34511598, 2021). "The MAP4K4 inhibitor also reduced MAP4K4 protein expression, tumor stroma, and induced cell death in murine pancreatic tumors." (PMID 34511598, 2021). "The phosphorylation of MLK3 by MAP4K4 promotes pancreatic cancer cell proliferation, migration, and colony formation." (PMID 34511598, 2021). "To rule out any non-specific effect of GNE-495 and confirm that MAP4K4 inhibition promotes cell death in pancreatic cancer cells, we knocked down MAP4K4 by using MAP4K4-specific siRNAs and determined cell death by flow cytometry and western blotting." (PMID 34511598, 2021). "Downregulating MAP4K4 in pancreatic cancer cells inhibits proliferation and invasion and enhances chemosensitivity." (PMID 31570734, 2019). "For example, miR-141 inhibits cell invasion by directly targeting MAP4K4 in pancreatic cancer, while it enhances apoptosis in PANC-1 cells by targeting Yes-associated protein-1." (PMID 30643007, 2019). "Overexpression of MAP4K4 is a poor prognostic factor for both overall and disease-free survival in patients with pancreatic cancer." (PMID 27023625, 2016). "On the other hand, MAP4K4 has been shown to be overexpressed in pancreatic cancer and other types of malignancies." (PMID 27023625, 2016). "On the other hand, MAP4K4 is overexpressed in most human cancer cells including pancreatic cancer and promotes tumor cell migration and invasion." (PMID 27023625, 2016). "Furthermore, F389-0746, a specific MAP4K4 inhibitor identified via virtual screening, significantly inhibits pancreatic cancer growth in subcutaneous models of nude mice and shows therapeutic potential." (PMID 41463025, 2025). "In addition, in vitro cell-based assays and an in vivo xenograft model were used to investigate the effects of the MAP4K4 inhibitor in pancreatic cancer." (PMID 36683274, 2023). "The expression of MAP4K4 is negatively regulated by microRNA-141 (miR-141) in pancreatic cancer." (PMID 37190200, 2023). "Therefore, we evaluated the MAP4K4 expression level of the two pancreatic cancer cell lines in this study." (PMID 36683274, 2023). "In vitro experiments were performed to understand the effect of the inhibitor in human pancreatic cancer cells, including a cell growth inhibition assay, cell viability assay, cell cycle analysis, and analysis of the MAP4K4 regulated JNK/c-Jun signalling pathway." (PMID 36683274, 2023). "Thus, a selective MAP4K4 inhibitor would suppress cell growth and proliferation in pancreatic cancer with less dysregulation of the Hippo signalling pathway." (PMID 36683274, 2023). "In summary, MAP4K4 plays an important role in pancreatic cancer." (PMID 36683274, 2023). "However, in-depth mechanistic studies are still required to establish MAP4K4 as a key player in pancreatic cancer." (PMID 37190200, 2023). "Another possible signalling pathway that RAP2 might modulate during the regulation of the malignant properties of pancreatic cancer might be the activation of mitogen-activated protein kinase (MAP4K4)." (PMID 35538031, 2022).
pancreatic cancer (continued). "Also in pancreatic cancer, miR-141, by directly targeting MAP4K4, increases the chemosensitivity of the cancer cells." (PMID 36158660, 2022). "Moreover, in pancreatic cancer cells, miR-141 acts as a tumor suppressor by targeting MAP4K4, which knockdown inhibits cell proliferation and induces G1 arrest and apoptosis." (PMID 36158660, 2022). "The MAP4K4 mRNA was significantly upregulated in pancreatic cancer tumors." (PMID 34511598, 2021). "Moreover, MAP4K4 is overexpressed in human pancreatic tumors and directly correlates with the disease progression." (PMID 34511598, 2021). "Therefore, inhibiting MAP4K4 activity in pancreatic tumours is a new therapeutic strategy." (PMID 36683274, 2023). "Therefore, activation of the MAP4K4 pathway might be another reason for RAP2-induced migration of pancreatic cancer cells." (PMID 35538031, 2022). "Therefore to determine the potential role of MAP4K4 in pancreatic cancer via MLK3 phosphorylation, stable pancreatic cancer cell lines, Capan-1 and AsPC-1 were created, expressing either doxycycline (DOX)-inducible MLK3 -WT or -T738A (phospho-deficient) or -T738D (phosphomimetic)." (PMID 34511598, 2021). "However, the mechanism by which MAP4K4 promotes pancreatic cancer is not fully understood." (PMID 34511598, 2021). "MAP4K4 binds to MLK3 and promotes phosphorylation at its Thr738 site, thereby activating MLK3 kinase activity to drive pancreatic cancer progression." (PMID 41463025, 2025). "MAP4K4-specific pharmacological inhibitor GNE-495 showed an antitumor response in in vitro and in vivo models of pancreatic cancers." (PMID 37190200, 2023). "A recent investigation demonstrated that MAP4K4-mediated phosphorylation and activation of mixed-lineage protein kinase 3 (MLK3) promoted pancreatic tumor proliferation, migration, and colony formation." (PMID 37223681, 2023). "The JNK/c-Jun pathway is the downstream signalling pathway mainly regulated by MAP4K4 and its downstream substrate MKK4 in pancreatic cancer cells." (PMID 36683274, 2023). "The MAP4K4-specific pharmacological inhibitor, GNE-495, impedes pancreatic cancer cell growth, migration, induces cell death, and arrests cell cycle progression." (PMID 34511598, 2021). "We used MAP4K4-specific pharmacological inhibitor GNE-495 that induced cell death and blocked cell cycle progression and migration of pancreatic cancer cells." (PMID 34511598, 2021). "Our list identified several genes that have been found to be activated in pancreatic cancer such as MET, MAP4K4, and ITGA2." (PMID 30092011, 2018). "In addition, MAP4K4 phosphorylates MLK3, a process that promotes pancreatic cancer cell proliferation, migration and colony formation." (PMID 41034525, 2025). "Thus, inhibiting the activity of MAP4K4 can down-regulate the JNK/c-Jun signalling pathway and suppress pancreatic cancer progression." (PMID 36683274, 2023). "Since MAP4K4 inhibitor GNE-495 was able to arrest cell cycle progression of pancreatic cancer cells line but not of the nontumorigenic cells, therefore we sought to determine the efficacy of GNE-495 on inducing cell death in pancreatic cells." (PMID 34511598, 2021). "Moreover, our data suggest that phosphorylation of MLK3 is necessary for the tumor permissive effects of MAP4K4, as the phospho-mimetic mutant of MLK3 (T738D) was sufficient to increase all the oncogenic characteristics of pancreatic cancer cells." (PMID 34511598, 2021). "For example, downregulation of the microRNA, miR-98-5p promoted pancreatic tumor development by downregulation of MAP4K4 and inhibition of the downstream MAPK/ERK signaling, suggesting that the miR-98-5p can be a therapeutic target in pancreatic cancer treatment." (PMID 30384450, 2018).
hepatocellular carcinoma (16 papers, 2014 to 2025). A malignant tumor that arises from hepatocytes. "Overexpression of MAP4K4 is associated with the activation of NF-κB and JNK signaling pathway and EMT induction in hepatocellular carcinoma (HCC)." (PMID 36905477, 2023). "The antitumor effects of MAP4K4 silencing were also observed manifested by reduced tumor xenograft growth in hepatocellular carcinoma." (PMID 36922678, 2023). "The following sections describe the role of MAP4K4 in colorectal and hepatocellular carcinoma, gastric cancer, and prostate and PDAC cancers." (PMID 37190200, 2023). "In hepatocellular carcinoma, MAP4K4 promotes EMT and invasiveness through activation of JNK and NF-kB signaling." (PMID 31570734, 2019). "Overexpression of MAP4K4 was identified as a prognostic indicator in multiple cancers, including hepatocellular carcinoma (HCC), PDAC, lung cancer, colorectal cancer (CRC) and prostate cancer." (PMID 29970191, 2018). "miRNA-194 acts as a prognostic marker and inhibits proliferation in hepatocellular carcinoma by targeting MAP4K4." (PMID 29118269, 2017). "Our results showed that HBV suppressed NFAT5 expression by inducing hypermethylation of the AP1-binding site in the NFAT5 promoter and inhibiting miR-30e-5p/MAP4K4/DARS2 pathway in hepatoma cells." (PMID 29052520, 2017). "Moreover, growing evidence shows MAP4K4 upregulation, e.g., in pancreatic ductal adenocarcinoma, hepatocellular carcinoma or lung adenocarcinoma, but the role of MAP4K4 in skin cancer development is to be elucidated." (PMID 40149574, 2025). "MAP4K4 was also reported to play a central role in focal adhesion dynamic, pancreatic tumorigenesis, chemosensitivity in cervical cancer, epithelial-mesenchymal transition and metastasis in hepatocellular carcinoma and tumor maintenance in lung adenocarcinoma." (PMID 36922678, 2023). "Our results showed that HBV could suppressed NFAT5 expression by inducing hypermethylation of the AP1-binding site in the NFAT5 promoter and inhibiting miR-30e-5p/MAP4K4/DARS2 pathway in hepatoma cells." (PMID 29052520, 2017). "Additionally, MAP4K4 is an independent prognostic factor for hepatocellular carcinoma and lung adenocarcinoma." (PMID 24708576, 2014). "EMT and invasion were facilitated by MAP4K4-activating JNK and NF-κB signaling, in hepatocellular carcinoma cells." (PMID 30429233, 2018). "Importantly, our findings, along with those of other researchers, revealed that a MAP4K4 inhibitor, GNE‐495, impedes hepatocellular cancer cell migration and invasion, indicating that MAP4K4‐targeting therapies may alleviate HCC progression." (PMID 38639383, 2024). "Current evidence indicates that MAP4K4 can potentially serve as a negative prognostic indicator in patients with colorectal cancer (CRC), hepatocellular carcinoma (HCC), pancreatic ductal adenocarcinoma (PDAC), lung adenocarcinoma and prostate cancer." (PMID 27800153, 2016).